CSF1 (colony stimulating factor 1)
Diseases named in the same sentence as CSF1 in open-access papers (continued):
Sharing a sentence is not in itself a finding about the gene and the disease.
tumor (continued). "This translocation leads to overexpression of CSF1 attracting CSF1R-bearing inflammatory cells which form the mass of the tumor." (PMID 33799327, 2021). "Its ligands are M-CSF (CSF-1), GM-CSF (CSF-2) and IL-34, and their binding to CSF-1R induces differentiation, recruitment to tumor sites, and the survival of monocytes and macrophages." (PMID 34638388, 2021). "Experimental evidence suggests that CSF-1/CSF-1R signaling attracts immune cells called macrophages into the tumor microenvironment which promote the capacity of cancer cells to spread." (PMID 34830923, 2021). "Now a day, inhibition of CSF-1/CSF-1R interaction by therapeutic antibody to deplete TAMs and their pro-tumor functions is becoming a prevalent strategy in cancer therapy." (PMID 33805444, 2021). "Macrophages are attracted to the circulation by various agents released from tumor cells, including CSF-1, CCL-2, VEGF, TNFα, or TGFβ, and accumulate at pre-metastatic sites." (PMID 33919517, 2021). "It was well documented that certain chemokines such as CCL2 and CSF-1 or CXCR2 ligands promoted the recruitment of MDSCs from the circulation to the tumor microenvironment." (PMID 33791296, 2021). "There is still evidence indicates the correlation between PTEN loss on tumor cells and elevation of immunosuppressive markers like IDO1, FOXP3, CCL2, CSF1 ect.." (PMID 33874915, 2021). "For example, downregulation of CCL2 reduces tumor growth in prostate cancers and inhibits cancer stem cell properties in breast cancers, and targeting CSF-1 can reduce TAMs and enhance the ratio of CD8+ to CD4+ T-cells." (PMID 34202411, 2021). "In this study, we surprisingly found a dramatic reduction in tumor sizes in mice treated with CXCL12/CSF1 neutralizing antibodies together with anti‐PD1 antibody, and CD8+ T cell infiltration was markedly increased." (PMID 33643790, 2021). "Immunohistochemistry analysis showed that CSF1 expression was markedly increased in senescent tumor cells." (PMID 33643790, 2021). "Classical monocytes recruited to tumor site by chemokines, including colony-stimulating factor 1 (CSF-1), chemokine (C-C motif) ligand 2 (CCL2), and chemokine (C-C motif) ligand 5 (CCL5), then polarized into M2 tumor-associated macrophages (TAMs)." (PMID 34141607, 2021). "RT also induces the release of colony-stimulating factor-1, CSF-1, from tumour cells, resulting in the expansion of TAMs and MDSCs." (PMID 34299373, 2021). "CSF-1R is exclusively expressed by cells of the monocytic lineage and, therefore, the CSF-1/CSF-1R axis has been extensively investigated in tumor models and is paradigmatic of the TAM-cancer cell interaction." (PMID 33731849, 2021). "Monocytic recruitment to the TME is often mediated by tumor-secreted soluble factors, such as CSF1 and CCL2." (PMID 34789744, 2021). "Blocking the CSF-1/CSF-1R signaling pathway interferes with tumor progression by regulating TAM, reducing tumor invasion and proliferation." (PMID 34729112, 2021). "Six have been indirectly linked to tumour malignancy and are thus new splicing targets to study (CAST, CSF1, PLOD2, SLK, SPAG9, TSC2)." (PMID 33845831, 2021). "One underlying mechanism depends on the ECM stiffening-induced tumor cell and CAF production of macrophage chemoattractants, such as CCL2 (C-C Motif Chemokine Ligand 2) and CSF1 (Colony Stimulating Factor 1)." (PMID 34298680, 2021). "Colon carcinoma cells are known to produce CSF-1, which recruits macrophages to the tumor periphery, where they secrete promotility and angiogenic factors that facilitate tumor cell invasion and metastasis." (PMID 34070480, 2021). "The infiltration of tumor-associated macrophages (TAMs) into the TME is mediated by MCP-1 and colony-stimulating factor 1 (CSF-1)." (PMID 32121320, 2020). "MDSC tumor-infiltration is mediated by CSF-1 and the combination of CSF-1/CSF-1R signalling inhibition with anti-CTLA-4 has been recently proposed." (PMID 32423420, 2020).
tumor (continued). "In the late stage of tumor progression (day 28), there was a reduction in the levels of Csf1, Mmp14, Nedd9, Nf2, Plaur, and Tgfb1 genes by all the investigated compounds." (PMID 32887237, 2020). "CSF-1, a cytokine crucial for the survival and differentiation of monocytes and macrophages, mediates the recruitment of MDSCs into the tumor niche, which in turn increases angiogenesis due to growth factor release." (PMID 33469537, 2020). "Any decrease in EGF or CSF1 will prevent tumor growth, a situation encountered with only the triple combination." (PMID 31938054, 2020). "Specific signaling molecules, such as CCL2, CSF-1, cytokines, and complement components (i.e., C5), are able to rapidly recruit circulating inflammatory monocytes at sites of tumor growth." (PMID 33050070, 2020). "Migratory macrophages can facilitate tumor cell movement towards blood vessels in the MMTV-PyMT model of breast cancer by forming physical contacts through an EGF/CSF1 paracrine loop." (PMID 33374595, 2020). "Blockade of Csf1/Csf1R, which is expressed by some TAMs, improved mouse survival and reduced tumor weight." (PMID 33584701, 2020). "Tumor cell-derived colony stimulating factor 1 (CSF1) promotes macrophage infiltration in the necrotic tumor area." (PMID 32219066, 2020). "CCL2 and CSF-1 are important for inflammatory monocyte recruitment into the tumor site and differentiation into TAMs." (PMID 33293516, 2020). "Genetic depletion or pharmaceutical inhibition of TAMs and CSF-1 restored the cytotoxic CD8+ T cell functions with tumor regression in mouse mammary and cervical models." (PMID 33343560, 2020). "Circ-ASAP1 was reported to facilitate HCC cell proliferating and invading processes by regulating miR-326/miR-532-5p-MAPK1 signaling and mediate tumor-related-macrophage infiltrating process through the control over the miR-326/miR-532-5p-CSF-1 path." (PMID 32665846, 2020). "GW2580 inhibits the growth of CSF1-dependent tumor cells and the recruitment of macrophages into growing tumours." (PMID 32581720, 2020). "The increase in circulating CSF-1 promotes the infiltration of MDSCs to tumor sites through the CSF-1/CSF-1R signaling pathway." (PMID 32942545, 2020). "Congruent with this, immunohistochemistry examination of soft tissue tumor patient samples showed increased expression of CSF-1 (M-CSF) and colony stimulating factor receptor (CSF1R) in more aggressive, higher histologic grade tumors." (PMID 33381449, 2020). "A proteomics study revealed that hypoxic tumour cells produced chemokines and immunomodulatory proteins, e.g., macrophage colony stimulating factor-1-rich exosomes that eluded host immunity and enhanced tumour progression." (PMID 33207810, 2020). "TAMs can arise from peripheral monocytes in response to a combination of CCL2 and CSF1 produced by the tumor." (PMID 32983100, 2020). "CSF-1/CSF-1R blockade promotes antitumor T cell responses and reduces tumor growth in several preclinical models in combination with immunotherapy, despite showing minor effects on tumor growth as a monotherapy." (PMID 32793228, 2020). "Exosomes from tumor cells package assorted proteins and chemokines with immunomodulatory capability, including CSF-1, CCL2, and TGF-β, to promote M2-like characterization of TAMs." (PMID 33505964, 2020). "TAMs increase tumor cell migration and invasion through a paracrine loop which consists of macrophage-derived EGF and tumor-induced CSF-1." (PMID 32326073, 2020). "Overexpression of miR-125b in testicular tumor cells significantly reduced the TAMs population at tumor site via inhibiting the production of tumor-promoting cytokines such as CSF-1 and CX3CL1." (PMID 32992449, 2020). "In a CSF-1 knockout mice model, macrophage number was found to significantly reduce in the tumor site, accompanied by impaired vascular development." (PMID 33251232, 2020).
tumor (continued). "In response to CSF1 (secreted by tumor cells), TAMs release the epidermal growth factor (EFG) that binds its receptor on the surface of tumor cells, activating signaling of motility, matrix degradation and invasion of the surrounding tissue." (PMID 32397392, 2020). "These cells are characterized by high plasticity and can be easily polarized by colony-stimulating factor-1, which is released by tumor cells, into an immunosuppressive M2-like phenotype." (PMID 32456078, 2020). "The treatment of patients with diffuse-type giant tumor cells with a CSF-1 antibody elicits objective response." (PMID 32775327, 2020). "We were unable to detect additional mutations in follow-up CSF ctDNA; however, we identified 3/5 mutations with a VAF < 1.5% that were previously detected in both tumour and CSF1." (PMID 33110059, 2020). "Intratumor hypoxia was shown to induce macrophage recruitment through HIF-dependent CSF1 secretion by tumor cells." (PMID 32286255, 2020). "CSF1 overexpression significantly increased mouse body weight (a surrogate marker of tumor burden), net tumor weight, ascitic fluid volume, and tumor implantation in peritoneum, omentum and pelvic cavity." (PMID 32286255, 2020). "On the other hand, our previous study found that CSF1-induced macrophage polarization toward M2 reversely promoted PD-L1 expression of tumor cell via PI3K/AKT/NF-κB/p65 activation." (PMID 33193421, 2020). "Mechanistically, NHWD-870 reduces the expression and secretion of macrophage colony stimulating factor 1 (CSF1) in tumor cells by blocking the functional activity of BRD4 and its target gene HIF-1α." (PMID 33109235, 2020). "The first and most widely used therapeutic macrophage-based strategy has been TAM depletion from tumor sites via the inhibition of colony stimulating factor-1/colony stimulating factor-1 receptor (CSF-1/CSF-1R) and CCL2/CCR2 inhibition." (PMID 32575899, 2020). "Mechanistically, CSF1 secreted by tumor cells binds to the CSF1R receptor on CAFs and inhibits the secretion of CXCL1 and other chemokines by CAFs to recruit PMN-MDSCs." (PMID 33224886, 2020). "On the contrary, tumor cell-derived paracrine signals contribute to M2-like macrophages, including IL-10, CSF-1, different chemokines (CCL2, CCL18, CCL17, and CXCL4), and various extracellular matrix components." (PMID 32653013, 2020). "In contrast, this report demonstrated that these tissue-resident macrophages are able to self-renew in tumors due to tumor-derived CSF-1 and promote tumor progression." (PMID 32655574, 2020). "NHWD-870 acts not only by directly suppressing the growth of tumor cells, but also by suppressing the proliferation of TAMs via downregulation of CSF1 in tumor cells." (PMID 32286255, 2020). "Taken together, these data showed that CSF1 is sufficient to promote OC growth by increasing the proliferation of TAMs and its downregulation in tumor cells contributes significantly to the tumor inhibitory effects of NHWD-870." (PMID 32286255, 2020). "M279, a CSF-1R antibody, blocking both CSF-1 and IL-34, has been shown to inhibit tumor growth and improve survival rate in a spontaneous breast tumor model." (PMID 33251232, 2020). "With respect to early tumourigenesis in mice, abrogation of CSF-1 signalling reduced tumour formation in mouse models of thyroid cancer and pancreatic neuroendocrine cancer." (PMID 32325966, 2020). "In turn, tumor cell-produced ligands such as colony-stimulating factor 1 (CSF1) signal to CSF1R on TAMs to promote recruitment and M2-like polarization." (PMID 32665556, 2020). "The CSF‐1 expression in tumour tissues was enhanced significantly compared with that in NBTs and correlated positively with tumour grade." (PMID 31994318, 2020). "Down-regulation of CSF1 weakens the activation degree of ERK1/2 and PI3K/AKT pathways, leading to decreased proliferation and survival of tumor associated macrophages (TAMs)." (PMID 33109235, 2020).
tumor (continued). "Confocal imaging also showed CD34high CAFs to be a source of CSF1 in the tumor stroma, but this was less specific at the protein level, with staining detected in other stromal populations." (PMID 32433953, 2020). "The reduction of infiltrating macrophages due to the blockade of CSF-1 and its receptor (CSF-1R) was shown to enhance the anti-tumor effect of docetaxel in a mouse model of epithelial OvCA." (PMID 32354198, 2020). "LC not only significantly reduced mouse body weight, net tumor weight, ascitic fluid volume and tumor implantation in these tissues at base line, but also completely abolished the effects of CSF1 overexpression." (PMID 32286255, 2020). "TAMs are recruited to the tumor site through tumor secretion of cytokines and chemokines, including ATP, CSF-1, CCL2, GDNF, GM-CSF HGF/SF, MCF-3, SDF-1, TNF and VEGF6,15." (PMID 32555306, 2020). "Tumor-derived CSF-1 recruits macrophages into the TME, resulting in increased IL-10 levels and defective anti-tumor CD8+ T cell responses." (PMID 32121071, 2020). "Two of the most studied therapeutic strategies to deplete TAMs from the tumor microenvironment are the inhibition of CSF-1/CSF-1R signaling and the use of liposomes containing clodronate." (PMID 32326073, 2020). "The direct or indirect induction of proinflammatory mediators, like IFNγ, IL4, IL6, IL13, VEGF, GM-CSF, CSF-1, Ang-2, CCL2 and other chemokines in the tumor milieu, has an antitumor effect linked to M1 polarization of TAM." (PMID 32708142, 2020). "The tumor-derived colony-stimulating factor-1 (CSF-1)/EGF paracrine loop helps in the recruitment of TAMs around the blood vessels, which promotes cancer cell escape through various mechanisms." (PMID 32992449, 2020). "The immunohistochemical assay revealed significantly down‐regulated levels of CSF‐1 and Ki67 in the tumour tissues of nude mice treated with miR‐1254 compared to that in controls." (PMID 31994318, 2020). "Transgenic expression of CSF1 resulted in a huge influx of TAMs into the primary tumor and led to accelerated growth and significantly increased the lung metastatic burden." (PMID 33374595, 2020). "Despite CSF-1 and CSF-2 distinctively influencing macrophages, the unique properties of the tumor immune microenvironment lead tumor-infiltrating macrophages toward the protumoral phenotype." (PMID 33505964, 2020). "CSF-1, produced by activated macrophages, lymphocytes, tumor cells, and other cells, can initiate and enhance the killing effect of macrophages." (PMID 32671118, 2020). "It is worth noting that hypoxia inducible factor-1 (HIF-1)-dependent production of CSF-1 in tumor cells recruits TAMs with hypoxia, which also means that improving the TME with hypoxia is beneficial to prevent the recruitment of TAMs." (PMID 33224886, 2020). "Tumor cells derived Colony Stimulating Factor 1 (CSF1) and C-C motif chemokine ligand (CCL) 2 leads to increased infiltration of macrophages in TME, which later increased angiogenesis by stimulating the secretion of vascular endothelial growth factor (VEGF)." (PMID 32219066, 2020). "More specifically, the tumor cells produce the colony-stimulating factor (CSF-1) leading to the attraction and growth of macrophages which in turn release epidermal growth factors (EGF) resulting in the growth and mobility increase of the tumor cells." (PMID 32221323, 2020). "Several studies show that blocking CSF-1/CSF-1R inhibited immunosuppressive macrophage polarization, reduced tumor cell proliferation, and promoted apoptosis, therefore suppressing tumor progression and prolonged life survival." (PMID 33251232, 2020). "The decrease of CSF1R amounts with the triple treatment argues strongly for a reduction in tumor growth since the CSF1/CSF1R pathway exerts an autocrine proliferation loop in RCC and CSF1R is indicative of poor prognosis." (PMID 31938054, 2020).
tumor (continued). "Its contribution to metastasis formation was demonstrated in a mammary cancer model where paracrine secretion of CSF-1 by tumor cells stimulated TAMs to migrate and provide a tract for tumors cells to follow along and invade normal tissue and vasculature." (PMID 33381449, 2020). "Correlation analyses showed that the CSF1 levels correlated significantly with the p-BRD4 levels in tumor cells (r = 0.5122)." (PMID 32286255, 2020). "CSF-1/CSF-1R signaling has undergone relatively explicit investigation so far, the well-known fact that CSF-1 can attract, polarize, and sustain TAMs infiltrating in the tumor microenvironment, especially in PDAC with affluent stroma." (PMID 33505964, 2020). "Circulating monocytes are recruited by several tumor-derived chemo-attractants as CCL2 (MCP-1), CCL3 (MIP-1), CXCL12 (SDF-1), and CSF-1 at tumor sites where they differentiate into TAMs and facilitate tumor progression." (PMID 33374253, 2020). "Monocytes are attracted and recruited to the tumor by chemokines such as colony stimulating factor 1 (CSF-1) which are secreted by tumor cells." (PMID 33050416, 2020). "Some trials utilizing monoclonal antibodies directed at CSF-1/CSF1R in adults exhibited limited anti-tumor activity (NCT01346358)." (PMID 33381449, 2020). "The blockade of this CSF-1/CSF-1R interaction presents an attractive approach for preventing the switching of tumor resident macrophages/microglia to the immunoinhibitory M2 phenotype." (PMID 33178210, 2020). "Zebrafish models of both brain and liver cancer have indicated that CSF-1 contributes to the recruitment of macrophages in response to tumour initiation." (PMID 32325966, 2020). "Subsequently, we co-cultured FOXO1(+) tumor cells with M0 macrophages in the presence of the anti-CSF-1 antibody and found that a percentage of the CD163+/CD68+ macrophages was significantly reduced." (PMID 33052231, 2020). "Tumor-associated macrophages (TAMs) are recruited by tumor cells via cytokines such as CSF-1 and IL-10 and converted into M2 macrophages, which have anti-inflammatory, angiogenic and tumor-promotive effects." (PMID 32514351, 2020). "Tumor- or CAF-derived cytokines also are able to induce monocytes recruitment within the tumor mass where they were activated to M1-like macrophages by CSF-1 and IFN-γ." (PMID 32266157, 2020). "CSF1 participates in the recruitment of TAMs to tumor tissues and the M2 polarization process of TAMs, and the survival, proliferation, and function of TAMs depend to a large extent on the CSF1R signaling." (PMID 33224886, 2020). "The disruption of the crosstalk between tumor cells and TAMs due to CSF1 and BAG3 depletion in an orthotopic PDAC tumor model enhanced Tc infiltration and activation, proving the importance of those soluble factors." (PMID 32823814, 2020). "High tumor stage and CSF-1 expression were correlated with a significant reduction in cancer-specific survival (HR = 6.03, CI = 2.17‐16.80, P = 0.001, and HR = 5.18, CI = 1.71‐15.71, P = 0.004, respectively)." (PMID 31565097, 2019). "Pharmacologic modulation of the tumor's ability to recruit TAMs cia CSF1 has shown efficacy preclinically." (PMID 31921140, 2019). "Third, a high level of CSF-1 positively correlated with tumor stage, tumor size, distant metastasis, and recurrence." (PMID 31565097, 2019). "Tumor-derived signals, such as Macrophage-Colony Stimulating Factor (M-CSF/CSF-1), Monocyte Chemoattractant Protein-1 (MCP-1), or Chemokine (C-C motif) Ligand-2 (CCL2) entails the accumulation of M2 at the tumor site." (PMID 31480382, 2019). "It was reported that both small molecular inhibitors and antibodies targeting either CCL2/CCR2 or CSF-1/CSF-1R signaling axis obviously inhibited the mobilization of monocytes and macrophages accumulation in tumor sites." (PMID 31300030, 2019). "In mouse mammary tumors, chemotherapy increased the expression of CSF-1 by tumor cells, followed by the recruitment of macrophages." (PMID 32038607, 2019).